ADAM10 (ADAM metallopeptidase domain 10)
Diseases named in the same sentence as ADAM10 in open-access papers (continued):
Sharing a sentence is not in itself a finding about the gene and the disease.
tumor (continued). "We also measured the protein levels of ADAM10 in tumor cells genetically modified for NME1 or NME2." (PMID 33918324, 2021). "The expression of ADAM10, Notch1, Notch2, Notch3, Notch4, Hey1, vimentin and N‐cadherin at the transcript level was significantly upregulated, whereas transcripts of E‐cadherin significantly decreased in tumour tissues versus in normal liver tissues of HCC." (PMID 33955149, 2021). "This might suggest that accumulation in the endolysosomal compartment of ADAM10 itself occurs together with some substrates, such as TNFα or FasL, in HL stromal and tumor cells upon treatment with ADAM10 inhibitors." (PMID 34067041, 2021). "In Cox proportional hazards model for multivariate survival analysis, pre-NACT ADAM10 (HR = 3.67, p = 0.028), Ki67 index (HR = 3.33, p = 0.049), tumor size (HR = 2.84, p = 0.045) and lymphatic metastasis (HR = 8.13, p = 0.002) had a statistically significant effect on overall survival." (PMID 33413403, 2021). "Furthermore, this panel revealed the potential colocalization of multiple tumor cell markers such as β-catenin, ADAM10, ZFX, and ZEB2." (PMID 34490110, 2021). "Tspan5 correlation analyses of TCGA tumour samples revealed that Tspan5 expression is positively correlated with the expression of ADAM10, Notch1, Notch2, Notch3, Notch4, Hey1, vimentin, N‐cadherin and Snail, whereas it is negatively correlated with E‐cadherin in HCC tissues." (PMID 33955149, 2021). "In addition, the ADAM-10 expression level was increased in RT-R-MDA-MB-231 tumor tissue compared to MDA-MB-231 tumor tissue and was even higher in CD24−/low/CD44+ tumor tissue." (PMID 34502547, 2021). "In addition, ADAM10 protein was found on the tumor cell membrane and blood vessel walls within tumor tissues, which was assessed using immunohistochemical analysis." (PMID 34638718, 2021). "In addition, ADAM10-mediated L1 cell adhesion molecule (LCAM) cleavage is reported to enhance tumor dissemination by increasing cell migration in ovarian and uterine carcinomas." (PMID 32269567, 2020). "On the one hand, we found that only two hub genes (CXCL10 and ADAM10) had negative associations with tumor purity." (PMID 32206083, 2020). "All together, these data strongly suggest that the relative action of ADAM10 versus ADAM17 in MICA/B shedding is a selective feature of a given tumor cell, probably because ADAM activity is regulated at multiple levels which may vary in different tumors." (PMID 32269567, 2020). "Notably, EV isolated from MSC of HL patients and HL tumor cell lines treated with the specific ADAM10 inhibitors retain the ability to inhibit shedding of the ADAM10 substrates MICA, tumor necrosis factor (TNF)α and CD30 in recipient cells." (PMID 32668783, 2020). "Nevertheless, in the tumor, mCX3CL1 may be cleaved by proteinases such as ADAM10 or TACE/ADAM17, which releases the chemokine domain and thereby reduces the level of mCX3CL1 on a tumor cell." (PMID 32466280, 2020). "Low levels of miR122 and miR144 in primary tumors may contribute to the up-regulation of both pro-metastatic genes ADAM10 and c-Met and may function as tumor suppressors in this disease." (PMID 32512881, 2020). "Given the important role of ADAMs in immunity and cancer, the present review highlights the relevance of platelet-derived ADAMs, in particular ADAM10 (herein referred to as pADAMs and pADAM10, respectively) for the role of platelets in cancer and tumor immunology." (PMID 32117229, 2020). "Inhibition of ADAM10 activity may have potential therapeutic benefit for this most aggressive tumor subgroup." (PMID 30661303, 2019). "In this study, we first indicate that the role of EGCG in APP and ADAM10 regulation is mediated by HuR, result in tumour cells apoptosis via HuR‐Erk1/2‐APP/ADAM10 pathway, adding a new dimension to EGCG‐mediated regulation of APP and ADAM10 in cancer cell apoptosis." (PMID 30793483, 2019). "ADAM10 has been described to impact tumour progression, chemoresistance, metastasis and invasion." (PMID 30651596, 2019).
tumor (continued). "One of the key features of ADAM10 is its sheddase activity that can generate ectodomain cleavage of various surface molecules such as growth factors, receptors and adhesion proteins, all reported to display crucial roles in tumour progression." (PMID 30651596, 2019). "Our results suggest a mechanism of irradiation-induced increased permeability and transendothelial migration of tumor cells based on the activation of ADAM10 and the subsequent change of endothelial permeability through the degradation and internalization of VE-cadherin." (PMID 31619190, 2019). "Moreover, we demonstrate that ADAM10 influences MPM progression by strongly enhancing tumour cell migration and invasion." (PMID 30651596, 2019). "Moreover, 5-FU increased and maintained membrane MICA (the ligand of NKG2D) expression on tumor cells through the inhibition of ADAM10." (PMID 27385218, 2016). "This is a critical step of the disease where the humoral response against ADAM10, or a reduced ADAM10 functionality, might confer an advantage in limiting the progression of the tumor." (PMID 27517630, 2016). "The auto-Abs to ADAM10 might rather reflect a peculiar molecular asset of the tumor in this group of patients, which in turn results in a limitation of the disease progression and a more favorable outcome." (PMID 27517630, 2016). "ADAM10 was highly expressed in the tumoral cells that seem to move out from the epithelia organization and in the budding area of the tumor invading the stroma." (PMID 27517630, 2016). "Therefore the presence of anti-ADAM10 Abs in patient sera can be considered as a favourable feature in patients with Crc at stage-III that undergo surgical resection of the tumor." (PMID 27517630, 2016). "In this context, it would be of interest to investigate whether the induction of auto-Abs to immature ADAM10 might reflect the activation of specific CD4+T helper cells able to foster an active anti-tumor response." (PMID 27517630, 2016). "In the future, it will be of interest to investigate the Crc expression levels of proprotein convertases and teraspanins as molecular characteristics of the tumor that might correlate with both the presence of anti-ADAM10 auto-Abs and the favourable prognosis." (PMID 27517630, 2016). "MiR-655-3p might functions as a tumor suppressor by directly targeting ADAM10 and indirectly regulating β-catenin pathway in the development of progression of HCC." (PMID 27259866, 2016). "In these patients, the reduced ADAM10 maturation might result in a decrease of sheddase activity that could reduce the proliferative and invasive capacity of tumor cells." (PMID 27517630, 2016). "Also, prognostic significance of ADAM-10 expression in primary tumor cells and metastatic lesion cells was evaluated during 5-year observation." (PMID 26266086, 2015). "Throughout the experiment, real-time RT-PCR analysis and immunohistochemical (IHC) analysis of the pathologic sections of these tumors showed that SB-treated tumor had increased miR-494 expression and decreased Bmi1 and ADAM10 expression in comparison to those from control HNC-TICs tumors." (PMID 26090866, 2015). "This suggests that ADAM10 activation might play a role in tumor initiation, subsequently enhancing proteolysis of substrates that could promote tumor progression and metastasis." (PMID 26440150, 2015). "ADAM10 may also promote tumor invasion and metastasis by degrading the extracellular matrix and affecting cell-cell signaling." (PMID 25333745, 2015). "Moreover, cytoplasmic ADAM10 and activated Notch1 were colocalized within these giant cells, suggesting that ADAM10/Notch1 signaling was activated in these angiogenic tumor cells." (PMID 24548763, 2014). "ADAM10 hydrolyzed FasL and contributed to apoptosis resistance of the tumor cells." (PMID 24520307, 2014). "ADAM10, as an active metalloprotease, influenced the tumor via numerous pathways and may have participated in apoptosis-related protein hydrolysis." (PMID 24520307, 2014).
tumor (continued). "Moreover, also the DN30 ability to inhibit HGF-dependent tumor cell scattering and invasiveness in vitro was shown to depend on ADAM-10." (PMID 22973229, 2012). "Furthermore, the modulation of the tumor microenvironment through the shedding of specific molecules by upregulated ADAM10 could influence crucial processes such as cell adhesion, migration, and immune evasion." (PMID 40746920, 2025). "Since these ECM proteins were modulated primarily in the context of tumours and the tumour microenvironment, and ECM deposition and fibrosis are particularly associated with cancer-associated fibroblasts (CAFs), this suggests a role for ADAM10 in modulating tumour–fibroblast crosstalk." (PMID 41226720, 2025). "Therefore, ADAM10/17 inhibitors (ADAMi) also decreased sICOSL levels in the tumor and serum." (PMID 40708008, 2025). "ADAM10 cleaves both Notch ligands and receptors, facilitating the gamma-secretase-mediated release of the Notch intracellular domain (NICD), which controls gene transcription programmes associated with cell fate decisions in normal and tumour development, tissue homeostasis, and angiogenesis." (PMID 41226720, 2025). "However, ADAM10 is responsible for the extracellular region shedding of a large variety of transmembrane proteins such as Notch, amyloid precursor protein, prion protein, growth factor/cytokine receptors, adhesion molecules, and tumor antigens." (PMID 38667323, 2024). "However, the cleavage of NKG2D ligands on tumor cells by ADAM10 damages this tumor‐lysis function." (PMID 37719444, 2023). "Interestingly, disintegrin and metalloproteinase domain-containing 10 (ADAM10) was upregulated in senescent tumor cells, and combined treatment with the ADAM10 inhibitor GI254023X and chemotherapeutic drugs inhibited MICA/B secretion and enhanced recognition and killing by NK cells." (PMID 35309907, 2022). "Similarly, tumor metastatic foci were also existed in four out of six nude mice in ADAM10 overexpressing group, but only one nude mouse had metastasis in lymph node tissue after ADAM10 being knocked down." (PMID 35551177, 2022). "Importantly, 8C7 preferentially bound ADAM10 from tumours versus that from normal tissues, indicating enhanced ADAM10 activity in tumours, and therefore the potential of 8C7 to be developed as a tumour-targeting agent." (PMID 35804938, 2022). "We previously showed that an active form of ADAM10 is elevated in tumours in both mice and humans, and that we could detect this active form using an antibody which we developed that binds to a specific region of ADAM10, which is apparently hidden in the inactive form." (PMID 35804938, 2022). "Moreover, metformin blocked tumor growth via the circ_0003214-miR-489-3p-ADAM10 axis in vivo." (PMID 34335751, 2021). "Therefore, ADAM10 may be provided as a helpful biomarker and therapeutic target in TNBC, and the inhibition of ADAM10 could reduce tumor growth, metastasis and chemo-resistance." (PMID 33413403, 2021). "We observed that CXCL10 and ADAM10 had negative associations with tumor purity." (PMID 32206083, 2020). "Thus, exosomal ADAM10 as a druggable target could serve to boost delivery of inhibitors, as well as to enhance tumor immunity." (PMID 32668783, 2020). "However, ADAM10 inhibition in cHL can be a double-edged sword because it might not only improve the therapy with anti-CD30 therapeutics but also favor the tumor-supporting, EV-based communication in cHL tissue." (PMID 32296414, 2020). "In summary, our data show that ionizing irradiation can activate the metalloproteinase ADAM10 in endothelial cells and thereby increase the vascular permeability through degradation and dislocalization of VE-cadherin, which facilitates transendothelial migration of tumor cells." (PMID 31619190, 2019).
tumor (continued). "Taken together, whereas the known α-secretase enzymes, mainly ADAM10 and ADAM17 (TACE) and in some degree ADAM9, are involved in APP α-secretase cleavage, they are not APP-specific and cleave various substrates associated with inflammation, tumor formation, and progression." (PMID 29560732, 2018). "Both publications suggests that ADAM10 may process putative barriers restricting tumor cells." (PMID 28367112, 2017). "In accordance with a reduced/aberrant processing and an increased expression of immature ADM10, the overall sheddase activity of ADAM10 could be reduced on the membrane of the tumor cells of the anti-ADAM10-positive patients, which in turn would result in an impairment of tumor growth and invasion." (PMID 27517630, 2016). "Furthermore, it was shown that ADAM-10 expression in the primary tumor (P = 0.029) was reduced with increasing age at diagnosis and that decreased expression of ADAM-10 in cancer cells from nodal metastases was also correlated with more advanced age at diagnosis (P = 0.037)." (PMID 26266086, 2015). "Our results also suggest that multinucleated giant cells are not osteoclasts, but angiogenic tumor cells in which ADAM10/Notch1 signaling is activated and might be implicated in tumor cell migration." (PMID 24548763, 2014). "Abnormal expression of metalloproteinases is regulated by HIF-1α, which induces the expression of MMP2, MMP9, ADAM10, etc., in tumor cells, hydrolyzing MICA and MICB on the surface of tumor cells and mediating immune escape." (PMID 40563539, 2025). "It was also reduced in our proteomic analysis of the secretome of ADAM10 KO SW620 cells, along with a number of other protein changes that are common to both tumour models, suggesting broader tumour relevance." (PMID 41226720, 2025). "In conclusion, our experiments show the wide effects of ADAM10 KO on protein shedding and expression in human GBM and CRC cells grown in vitro, and the inhibition of tumour xenografts in mice." (PMID 41226720, 2025). "The expression of most proteins tended to increase from the primary tumor to the corresponding metastasis, except for cellular CTNND1 and both cellular and stromal ADAM10." (PMID 40075679, 2025). "Published data show that several ADAMs, including ADAM8, ADAM9, ADAM10, ADAM12, and ADAM17, are overexpressed in tumours." (PMID 40427200, 2025). "In the current study, a positive correlation was shown between both ADAM10 and ADAM17 concentrations in the tumor tissue and the surgical margin." (PMID 39940871, 2025). "Design suppressor drugs targeting tRF-3021a to down-regulate the expression of ADAM10 protein, maintain the expression of membrane protein MICA, reduce soluble MICA, and remove the immune escape of tumor cells to NK cells." (PMID 40726981, 2025). "The analysis of ADAM10 and ADAM17 concentrations in the tumor tissue and surgical margin in CRC patients and their analysis, depending on selected parameters, were presented in our previous study." (PMID 39940871, 2025). "Another study showed that the concentrations of ADAM10 and ADAM17 in the tumor tissue and surgical margin of CRC patients differ." (PMID 39940871, 2025). "Correlations between ADAM10 and ADAM17 concentrations in the tumor tissue and surgical margin, as well as NLR and PLR values, were also examined." (PMID 39940871, 2025). "We assessed the role of ADAM10 by gene knockout (KO) in U251 GBM cells, and its effects on protein shedding and protein expression on cell proliferation and on the growth of tumour xenografts in mice." (PMID 41226720, 2025). "The first circuit requires light-induced activation of retinal ganglion cell (RGC) neurons and the release of ADAM10, which cleaves membrane-bound NLGN3 from OPCs to drive tumor initiation." (PMID 41497446, 2025). "Lastly, to relate our findings to human tumours, we used the TCGA database to compare ADAM10 expression in human GBM to the expression of the protein sets we identified as being modulated by ADAM10." (PMID 41226720, 2025).
tumor (continued). "In a previous study, we analyzed the concentration of ADAM10 and ADAM17 in the tumor tissue and surgical margin in patients with CRC and the role of these proteins in other diseases dependent on the inflammatory process, such as DMT2 or CVD." (PMID 39940871, 2025). "In NB, senescent tumor cells overexpress the lncRNA MALAT1, which regulates the expression of ADAM10 metalloproteinase and the consequent release from tumor cells of the NKG2D ligand MICA/B." (PMID 40496868, 2025). "Tumours also displayed significantly less staining for CD31+ endothelial cells, and the stem cell marker CD133, consistent with ADAM10 promoting a more stem-like, poorly differentiated phenotype." (PMID 41226720, 2025). "The aim of the study was to assess NLR and PLR and their relationship with selected clinical parameters in CRC patients, as well as the correlation between ADAM10 and ADAM17 in tumor tissue and matched surgical margins with NLR and PLR values." (PMID 39940871, 2025). "ADAM10 has been observed to be excessively expressed in HCC tissues, significantly correlating with tumor progression and reduced survival rates." (PMID 39346916, 2024). "This suggests that both ADAM10 and ADAM17 play crucial roles in regulating the PD-L1/PD-1 pathway which in turn impacts anti-tumor immunity." (PMID 38317965, 2024). "Additionally, HIF-1α increases the expression of a protein called ADAM10 (a disintegrin and metalloproteinase domain-containing protein 10) in cancerous cells, causing major histocompatibility complex class I chain-related molecule (MICA) to be shed from a tumor cell's surface." (PMID 38165484, 2024). "It is shown that suppressing cleavage of HER2 by INCB7839 (an ADAM10/ADAM17 inhibitor) decreases soluble HER2 ECD formation and also membrane p95 levels and subsequently renders tumor cells' response to treatment with trastuzumab." (PMID 38317965, 2024). "Compared with the selective inhibitor of ADAM10 (GI254023X), the ADAM17 inhibitors JG26 and aderbasib effectively reduced the permeability and tumor cell adhesion induced by EMT-HCT116 exosomes." (PMID 38413999, 2024). "Although several different ADAMs have been implicated in cancer initiation and progression, as well as conferring resistance to specific cancer therapies in various tumour types, ADAM17 and ADAM10 remain as the two most important metalloproteases." (PMID 38600326, 2024). "Some of the ADAMs, such as ADAM9, ADAM10, ADAM12, ADAM15, and ADAM17, are frequently upregulated in tumor tissues as well as cancer cell lines, and their expression often correlates with adverse patient survival and/or treatment response." (PMID 37495855, 2023). "For instance, platelets express “a disintegrin and metalloproteinase” (ADAMs) on their surfaces, and one of the members called ADAM10 participates in the shedding of the stress‐induced NKG2D ligands such as MICA/B and ULBP2 on tumor cells." (PMID 37719444, 2023). "Platelets can express both ADAM10 and ADAM17that can induce the shedding of NKG2D from tumor cells, thereby suppressing NK cell anti-tumor immune function." (PMID 37153586, 2023). "(D) Heatmaps showing expression of ICAM1 and ICAM-1 cleavage related proteases MMP9, ELANE, CTSG, ADAM10, and ADAM17 in normal or tumor tissue of 22 different cancer types." (PMID 37732732, 2023). "H. pylori-induced chronic inflammation upregulates ADAM10 and ADAM17 expression, resulting in increased shedding of membrane-bound TNFRs or EGFR ligands, and is related to tumor proliferation and lower patient survival rates." (PMID 36572816, 2023). "CRC cells advance as ADAM10 and ADAM17 cleave mMICA or membrane-bound IL-6R in the tumor microenvironment, and furthermore, the shedding of membrane-bound L1-CAM influences metastasis." (PMID 36572816, 2023).